NRAS (NRAS proto-oncogene, GTPase)
Diseases named in the same sentence as NRAS in open-access papers (continued):
Sharing a sentence is not in itself a finding about the gene and the disease.
melanoma (continued). "BRAFV600E, or RAS with BRAF and NRAS mutated cell lines, showed higher levels of DUSP6 expression, compared to melanoma cell lines carrying wild type BRAF and NRAS." (PMID 31416288, 2019). "To identify more effective therapies for NRAS‐mutant melanoma, we evaluated combinations of JQ‐1 with inhibitors of RAS effectors that are undergoing clinical evaluation for NRAS‐mutant melanoma patients." (PMID 29650805, 2018). "One of these patients and two others subsequently developed distant metastases in lung (single 7‐mm lesion, subsequently resected revealing BRAF V600E melanoma, undetected by ctDNA), liver (BRAF V600E, detected), and kidney (NRAS Q61R, detected)." (PMID 30113761, 2018). "siRNA‐mediated knockdown of NEK9 using siRNA pools from two manufacturers (siNEK9#1 and #2) reduced the growth of both BRAF‐mutant (1205Lu) and NRAS‐mutant (WM1366, IPC‐298, and M245) melanoma cell lines." (PMID 29112787, 2018). "One possible strategy to delay the clinical onset of resistance is to co-administer drugs that inhibit the ability of initial NRAS or KRAS-mutant clones to proliferate, as has been suggested previously with 17-AAG and melanoma." (PMID 29481571, 2018). "Hence, the information about the presence or absence of a certain mutation in BRAF or NRAS or KIT is not sufficient to predict whether or not a melanoma cell will enter the brain." (PMID 30053879, 2018). "In both the 1205Lu BRAF‐mutant melanoma cell line and the WM1366 NRAS‐mutant melanoma cell line, treatment with dabrafenib, but not vemurafenib, led to abrogation of RB protein phosphorylation and strong upregulation of p27." (PMID 29112787, 2018). "Strikingly, this was consistently observed in NRAS and BRAF mutant, as well as in ‘wild type’ melanoma cells." (PMID 30405888, 2018). "Strikingly, results of this study reveal that this finding holds true for NRAS and BRAF mutant, as well as ‘wild type’ melanoma cells." (PMID 30405888, 2018). "In the vast majority of progressing melanomas, resistance occurs via the re-activation of MAPK signalling, commonly via alterations in BRAF, NRAS and MEK1/2." (PMID 30237495, 2018). "As FOSL1 (Fra-1) links the BRAF/NRAS pathway to TWIST (see Discussion below), we chose to verify the microarray results from the xenograft experiment in the patients’ melanoma samples by staining for FOSL1." (PMID 30089785, 2018). "Interestingly, melanoma with NRAS mutations virtually never presents BRAF mutations." (PMID 29371600, 2018). "Here we show that BRAFWT, at least in the context of activated NRAS in melanoma cells, binds to HSP90 in melanoma cells in a complex with CRAF." (PMID 29481571, 2018). "To identify any potential cooperation between the common oncogenic alterations with DOT1L mutation in melanoma development, we first analyzed the relationship between BRaf/NRas status and DOT1L status in the TCGA melanoma cohort." (PMID 29343685, 2018). "Taken together, these results show that RAF signalling is absolutely required downstream of NRAS, and disclose both specific and compensatory functions for BRAF and CRAF kinases in NRAS-induced mouse melanoma." (PMID 28497782, 2017). "Among 253 melanomas, 129 (51.0%) BRAF, 45 (17.8%) NRAS, 6 (2.4%) KIT, 4 (1.6%) GNAQ, 2 (0.8%) GNA11, 2 (0.8%) MAP2K1 and no MAP2K2 gene mutations were detected by the biochip assay." (PMID 28881731, 2017).
melanoma (continued). "In order to compare NGS with conventional molecular testing under routine laboratory conditions, we calculated the turn-around time and costs for three commonly melanoma-related genes (BRAF, NRAS, KIT) in eight samples." (PMID 28356599, 2017). "Melanomas (skin) are indeed an outlier, as both BRAF and NRAS-mutant cells are particularly sensitive to all forms of MAPK inhibition." (PMID 28649441, 2017). "In all HET melanomas, non LOH of NRAS locus surrounding microsatellites was detected but one for which microsatellites presented a low LOH, near the upper LOH detection threshold." (PMID 28668077, 2017). "The results here suggest that the use of a combination of MCL-1 and BCL-2 inhibitors to induce NOXA and BIM is a promising treatment strategy for melanoma regardless of the mutation status of BRAF or NRAS, and it may overcome melanoma's resistance to current treatments." (PMID 27086916, 2017). "For example, if testing for melanoma is done using a combination of three single gene tests for BRAF, NRAS, and KIT, this costs less than the panel." (PMID 28196074, 2017). "Similar selectivity and efficacy of trametinib was also reported as a single-agent in wild-type BRAF/NRAS, NF1-altered melanomas." (PMID 29156677, 2017). "In two melanoma cell lines (SK-Mel29, WM1366), Usp9x activated NRAS promoter activity by ∼2-fold, while Ets-1 expression increased promoter activity by >2.5-fold." (PMID 28198367, 2017). "Indeed, although NRAS or BRAF mutations represent the main force driving melanoma development, they are not “per se” sufficient since these mutations are also present in benign nevi, thereby highlighting the requirement of other factors to drive melanocyte transformation and melanoma development." (PMID 28491820, 2017). "Deletion of NRAS was also a rare event and was observed in 9.4% (3/32) of BRAF/NRAS WT and 3.3% (1/30) of HET melanomas." (PMID 28668077, 2017). "In the present analysis, NRAS-mutant cells activated the AXL program and BRAF/NRAS wild type cells the MITF program which also resembles the melanoma pigmentation subtype described earlier." (PMID 27903987, 2017). "In this study, we found that the EPE peptide significantly reduced the viability of not only BRAF, but also several NRAS and NF1 mutant melanomas." (PMID 29180761, 2017). "Toward this end, we knocked down the expression of IFI6 in three NRAS-mutant melanoma cell lines (YUGASP, M318, and SKMEL-103) and one NRAS wild-type melanoma cell line (YUVON) and monitored their colony- and tumor-forming ability." (PMID 27608486, 2016). "The greater susceptibility to Prima-1 ± 3-BrPA in hypoxic mutant NRAS MelJuso melanoma (Summary), suggests that agents like Prima-1 + 3-BrPA, may help attenuate the frequent acquisition of resistance to targeted therapy against V600E BRAF-mutated tumors which acquire NRAS mutations." (PMID 27863474, 2016). "However, hyper-activation of the MAPK-pathway is found in over 90% of melanomas with approximately 50% of all patients displaying mutations in the kinase BRAF, and approximately 28% of all patients harboring mutations in the MAPK-pathway up-stream regulator NRAS." (PMID 27200346, 2016). "We report here for the first time that miR-32 behaves as a tumor suppressor miRNA in melanoma by inhibiting the expression of MCL-1, as well as its upstream effectors NRAS and PI3K." (PMID 27846237, 2016). "Accordingly, the viability of melanoma cells freshly isolated from a patient at 72h with a wild-type BRAF and NRAS status also largely decreased upon NS1 treatment." (PMID 27756874, 2016). "Likewise, although double-mutated NRAS/BRAF melanoma cultures have been previously reported, these may still represent heterogeneous mixtures of singly-mutated melanoma cells, or may have arisen artificially through in vitro drug treatment and selection experiments." (PMID 27791198, 2016).
melanoma (continued). "Remarkably, we found that simultaneous treatment of NRAS-mutant cells with the MEK inhibitor trametinib and either hydroxyurea or aphidicolin resulted in significantly stronger melanoma growth inhibition in cell culture and in mice than either drug alone." (PMID 27608486, 2016). "In the old situation within specialised hospitals, we assumed that multiple single-gene tests were performed, minimally three for NSCLC patients (a multigene panel, HER2/EGFR, and ALK, ROS, RET, or MET) and two for melanoma patients (BRAF and NRAS or KIT)." (PMID 27899957, 2016). "Two cell lines with focal ETV1 amplification demonstrated ETV1 dependency in melanoma proliferation, and ETV1 co-expression with oncogenic mutant NRAS or BRAF demonstrated enhanced proliferation." (PMID 26158900, 2015). "As for the remaining cohorts, 30 and 41 patients with NRAS- and BRAF-mutant melanomas, respectively, received MEK162 45 mg twice daily." (PMID 26171394, 2015). "In this study we performed the molecular appraisal of BRAF, NRAS, CKIT and EGFR genes altogether in a highly selected cohort of melanoma patients with lung metastases, that had been surgically treated with curative intent." (PMID 26305188, 2015). "Neuroblastoma v-ras oncogene homolog (NRAS) and v-raf murine sarcoma viral oncogene homolog B1 (BRAF) are oncogenes in melanoma, which are critical for tumor initiation." (PMID 26095858, 2015). "Since NRAS mutations are found in 18% of MM and are furthermore observed as an escape mechanism against first-line vemurafenib treatment in BRAF-mutant MM, MEK-inhibition could represent a promising therapeutic target to enhance the susceptibility of melanoma cells to therapy-induced DNA damage." (PMID 26136337, 2015). "However, the study did not include melanoma cells with known NRAS mutation." (PMID 25646931, 2015). "With the many available active anti-melanoma agents, the optimal treatment algorithm for various subsets of patients, e.g. BRAF mutants, NRAS mutants, PD-1 expressing, has yet to be determined." (PMID 27508107, 2015). "Next three genes in the order of decreasing cross-talk frequency are NRAS (cf = 41), RAF1 (cf = 38) and PTPN11 (cf = 38)- the genes are known for its aberrant behaviour in melanoma." (PMID 26558755, 2015). "The optimum treatment for other subsets, including NRAS-, GNAQ- or GNA11-mutant melanomas, remains to be determined." (PMID 26084293, 2015). "Our results demonstrated that RICTOR cooperates with oncogenic NRAS by increasing AKT activation and stimulating clonogenicity of melanoma cells." (PMID 26356562, 2015). "We found that mutNRAS melanoma cells are significantly more resistant to two bona fide IMPDH inhibitors (MPA and AVN944), suggesting that in NRAS mutant cells IMPDH activity or its downstream signalling is elevated." (PMID 24941944, 2014). "In the current study, BRAF and NRAS mutational status was not identified as a prognostic marker in stage III melanoma patients with macroscopic nodal involvement, but had a neutral role in terms of patient survival, which may be of importance for potential adjuvant therapy." (PMID 24959217, 2014). "The sensitivity profiles to the inhibitors of the two key NRAS downstream signaling cascades MAPK and PI3K/AKT/mTOR were similar to sensitivity profiles found in NRAS mutant melanoma." (PMID 25277205, 2014). "Significantly mutated gene analysis using 13 WGS cases and 15 additional paired extension cases identified known melanoma genes such as BRAF, NRAS, and CDKN2A, as well as a novel gene EPHA3, previously implicated in other cancer types." (PMID 25393105, 2014). "It should be noted that in melanoma, BRAF and NRAS mutants can in some cases coexist in the same tumour in contrast with colorectal cancer." (PMID 25361007, 2014).
melanoma (continued). "Fourteen NRAS mutant melanoma and seven cells lines with wild-type BRAF and NRAS were evaluated for SCH772984 sensitivity." (PMID 25142146, 2014). "MeWo (BRAF wildtype, NRAS wildtype), SkMel28 (BRAF V600E mutant, NRAS wildtype), HT144 (BRAF V600E mutant, NRAS wildtype) and UACC62 (BRAF V600E mutant, NRAS wildtype) melanoma cell lines were screened for PTEN protein." (PMID 24830350, 2014). "Our in silico significance and proximity analysis of 28 paired cases (13 WGS and 15 targeted cases) identified known (e.g., BRAF, NRAS, CDKN2A, and GRIN2A) and novel (e.g., EPHA3, GRIN2B, and ASXL3) genes involved in melanoma." (PMID 25393105, 2014). "It is now accepted that genetic lesions in BRAF and NRAS have different consequences in melanoma formation and it is becoming apparent that BRAF can regulate invasion and metastasis through mechanisms different to NRAS." (PMID 24941944, 2014). "We monitored miR-146a expression in a panel of BRAF/NRAS wild-type or BRAF or NRAS mutant melanoma cell lines, short-term patient-derived melanoma cultures and melanocytes." (PMID 24550252, 2014). "Whereas BRAF only activates the MAPK-pathway, NRAS activates several other effectors including Ral-GDS or PI3-kinase, which is of special relevance for melanoma." (PMID 24941944, 2014). "Several oncogenes have been identified in melanoma as BRAF, NRAS, c-Kit, and GNA11 GNAQ, each capable of activating MAPK pathway, although NRAS and c-Kit also activate PI3 kinase pathway, including being more commonly BRAF activated oncogene." (PMID 23476798, 2013). "A typical example of a genomic panel recommended for cancer diagnosis is a panel comprising of BRAF, KIT, NRAS, GNA11 and GNAQ for Melanomas." (PMID 23863689, 2013). "In another study involving melanomas, C-MYC overexpression was found to be required for the continuous suppression of BRAF(V600E) or NRAS(Q61R)-induced senescence." (PMID 24130815, 2013). "As a result, NRAS remains in its active, GTP-bound state driving cell proliferation, survival and motility making NRAS an important therapeutic target in melanoma." (PMID 23660168, 2013). "Melanomas arising in chronically sun-damaged skin, mucosal surfaces, and acral skin were characterized by wild-type BRAF and wild-type NRAS but exhibited alterations in KIT." (PMID 24416617, 2013). "HAGE was shown to promote proliferation and tumor growth of this subpopulation of melanoma cells, and to regulate AKT and ERK phosphorylation through NRAS." (PMID 23116066, 2012). "Interestingly, the amplification of CCND1 is relatively rare in melanomas with BRAF-NRAS mutations and may have similar effects on melanoma cell growth as the activation of the mitogen-activated protein kinase (MAPK) signaling pathway resulting from BRAF and/or NRAS mutations." (PMID 21911917, 2011). "Comparison of genes amplified in our samples with published gene lists from two large melanoma studies while revealing very little overlap did identify BRAF, MDM2, and NRAS, genes known to be important in melanoma." (PMID 21494657, 2011). "Two human melanoma cell lines were used: CHL-1 with WT BRAF/WT NRAS and SKMEL28 with V600E mutant BRAF/WT NRAS." (PMID 21037799, 2010). "We here examined the relationship between alterations in NRAS, BRAF, and p16CDKN2A genes in both in vivo melanoma tissues (N = 35) from southern Italian patients and in vitro melanoma cell lines (N = 18)." (PMID 19799798, 2009). "NRAS had been investigated as a target for melanoma therapy, but no NRAS-targeting small molecule inhibitor has been approved for clinical approaches." (PMID 40473796, 2025).
melanoma (continued). "Previous studies have identified several molecular drivers of melanoma that affect aerobic glycolysis and OXPHOS, as well as the expression levels of peroxisome proliferator-activated receptor-γ coactivator-1α (PGC-1α), BRAF, and NRAS." (PMID 40404919, 2025). "Moreover, melanoma consists of distinct molecular subtypes (e.g., BRAF-mutant, NRAS-mutant, triple wild-type), each with unique gene expression profiles." (PMID 40722520, 2025). "Comprehensive molecular profiling, including common melanoma-associated mutations in BRAF, NRAS and the GNAQ/GNA11 signaling pathway, was not performed in this case." (PMID 41294657, 2025). "Lastly, the TWT melanoma subtype is characterized by the absence of mutations in the three most common melanoma driver genes, namely BRAF, NRAS, and NF1." (PMID 40867277, 2025). "In melanoma, senescence may arise as a result of oncogenic BRAF or NRAS activation, therapeutic stress, or immune‐mediated signals." (PMID 40926366, 2025). "Melanoma is an aggressive form of skin cancer, and patients with NRAS-mutant melanoma face limited treatment options due to the lack of direct NRAS inhibitors." (PMID 40473796, 2025). "NRAS mutant melanoma accounts for approximately 15–20% of melanoma cases and is characterized by a more aggressive clinical course compared to BRAF mutant melanoma." (PMID 40867277, 2025). "Our findings suggest that, conversely to non-mutated melanomas, BRAF, NRAS, and cell cycle gene-mutated melanomas were significantly associated with clinical, histopathological, and dermoscopic characteristics underlying a more aggressive melanoma phenotype." (PMID 40867317, 2025). "By contrast, mucosal and other non-cutaneous melanomas have lower rates of BRAF and NRAS mutations and higher frequencies of KIT and other alterations." (PMID 41384184, 2025). "One study investigated the relationship between pre-treatment and the early on-treatment detection of BRAF, NRAS and KIT alterations in ctDNA using ddPCR and treatment outcome in 76 melanoma patients treated with nivolumab alone or in combination with ipilimumab." (PMID 39859576, 2025). "NRAS ASO-1 treatment did not significantly reduce cell growth in primary human melanocytes (the cell type that melanoma derives from), primary human liver cells, epithelial human colon cells, or NRAS-WT melanoma cells." (PMID 40473796, 2025). "In contrast, oncogenic NRAS mutations, which do not co-occur with BRAF mutations, are present in approximately 15–25% of melanoma cases." (PMID 39859576, 2025). "Additionally, targeting NRAS‐mutant melanoma, strategies have centered on downstream MAPK blockade because direct pharmacologic inhibition of mutant NRAS has remained intractable." (PMID 41199020, 2025). "In contrast, ddPCR methods are far more economical, but the mutational profile must be known in advance, and >20% of melanoma patients do not harbor a known driver genomic alteration, which are known to be BRAF and NRAS-wt." (PMID 39859576, 2025). "For example, triple wild-type melanomas, which are melanomas lacking mutations in BRAF, NRAS, and NF1, exhibit markedly low TMB compared to NF1-mutant melanomas." (PMID 40004731, 2025). "Thus, Cobi+Reg produced marked antitumor efficacy in multiple PDX lines encompassing the major molecular subtypes of melanoma (i.e., BRAF-, NRAS-, and NF-1–mutant) developed after progression on PD-1–based ICB." (PMID 40638246, 2025). "However, in approximately 30% of melanoma cases that are wild-type (wt) for both BRAF and NRAS, ctDNA analysis is more challenging." (PMID 39859576, 2025). "NRAS ASO treatment induced apoptosis and robustly decreased cell growth and colony formation in NRAS-mutant melanoma cell lines in vitro, without significantly affecting the growth of non-malignant NRAS wild type (WT) cell lines." (PMID 40473796, 2025).